MERTK (MER proto-oncogene, tyrosine kinase)
Diseases named in the same sentence as MERTK in open-access papers (continued):
Sharing a sentence is not in itself a finding about the gene and the disease.
hemorrhagic stroke (3 papers, 2021 to 2024). A stroke caused by a bleed on the brain. "Our immunostaining and in situ hybridization results demonstrated that MEGF10 and MERTK were upregulated in both reactive microgliosis and astrogliosis after ischemic or hemorrhagic stroke." (PMID 34836962, 2021). "Conditional knockout of MEGF10 or MERTK in microglia/macrophages attenuated the phagocytosis of synapses, which was shown to be helpful for improving dendritic spine structure and neurological dysfunction in an ischemic and hemorrhagic stroke mouse model." (PMID 38727249, 2024). "In this study, we revealed that at the poststroke repair and remodeling stage, reactive microgliosis and astrogliosis were active in engulfing synapses through MEGF10- and MERTK-related pathways, but showed different temporal phagocytic features in ischemic and hemorrhagic stroke." (PMID 34836962, 2021). "However, specific MEGF10KO and MERTKKO in astrocytes did not affect the number of spines, suggesting that microglia/macrophages but not astrocytes played a critical role in engulfing dendritic spines via MEGF10 and MERTK after hemorrhagic stroke." (PMID 34836962, 2021). "Moreover, specific MEGF10KO or MERTK KO in microglia/macrophages improved neurobehavioral outcomes of mice after hemorrhagic stroke, while MEGF10KO or MERTK KO in astrocytes did not affect neurobehavioral outcomes." (PMID 34836962, 2021).
kidney cancer (3 papers, 2019 to 2024). Primary or metastatic malignant neoplasm involving the kidney. "This work provides a mechanism underlying MERTK-mediated Akt activation and survival signaling in kidney cancer." (PMID 30944303, 2019). "Although mechanisms are not fully understood, REGγ and MERTK also appear to impact core Hippo pathway components during kidney cancer progression." (PMID 39123485, 2024).
liver cancer (3 papers, 2018 to 2025). An epithelial or non-epithelial malignant neoplasm that arises from the liver. "In a recent preclinical study on liver cancer, researchers found that Mer proto-oncogene tyrosine kinase (MerTK) enhances SLC7A11 expression via the ERK/SP1 signaling pathway." (PMID 40012016, 2025). "Interestingly, recurrent MERTK fusions are singletons in each individual cancer type with TMEM87B, and PRKACA fusions are observed only in liver cancer with DNAJB1." (PMID 29617662, 2018).
lymph node metastasis (3 papers, 2016 to 2024). "Higher expression of MerTK was positively associated with lymph node metastasis in GC patients, and knockout of MerTK reduced tumor growth and colony formation capability." (PMID 38545840, 2024). "Patients with a high MerTK expression status had a higher risk of lymph node metastasis in the postoperative specimens." (PMID 38545840, 2024). "This was confirmed using overexpression, knockdown and inhibition experiments and is underlined by the fact that higher MERTK protein and mRNA expression correlate with the occurrence of lymph node metastases." (PMID 27081701, 2016). "Our results showed a decreased number of soft agar colonies after MerTK dysfunction, which may explain why patients with high MerTK expression were more likely to have lymph node metastasis." (PMID 38545840, 2024). "In patients, high MerTK expression was associated with decreased overall survival (OS) and lymph node metastasis especially in patients without neoadjuvant therapy (p < 0.05)." (PMID 38545840, 2024). "Expression of MERTK and/or AXL provides a survival advantage for NSCLC cells and correlates with lymph node metastasis, drug resistance, and disease progression in patients with NSCLC." (PMID 34830794, 2021).
metastatic tumor (3 papers, 2017 to 2025). "If MerTK is associated with tumor survival and metastasis, patients with metastatic disease may show more frequent MerTK expression." (PMID 29228560, 2017). "Similar reduction in metastatic tumor burden was found with MerTK inhibition in the spontaneous liver metastasis model, whereas primary tumors remained unaffected." (PMID 38355776, 2024).
osteoarthritis (3 papers, 2023 to 2025). A noninflammatory degenerative joint disease occurring chiefly in older persons, characterized by degeneration of the articular cartilage, hypertrophy of bone at the margins and changes in the synovial membrane. "The activation of the AMPK/Gas6/MerTK/SOCS3 signal pathway by ozone also provides new theoretical evidence for ozone treatment of osteoarthritis." (PMID 38066599, 2023). "In osteoarthritis, impaired efferocytosis and elevated levels of apoptotic cells have been observed in synovial tissues, which have been linked to the deficiency of membrane-bound TAM receptors (Tyro3, AXL, and MERTK)." (PMID 40458640, 2025).
pancreatic cancer (3 papers, 2017 to 2025). "The receptor tyrosine kinases TAM family (TYRO3, AXL, and MERTK) are highly expressed in multiple forms of cancer cells and tumor-associated macrophages and promote the development of cancers including pancreatic tumor." (PMID 37475048, 2023). "However, AXL and MERTK were up‐regulated in renal clear cell carcinoma and pancreatic cancer." (PMID 40576208, 2025). "MERTK is down‐regulated in KRAS‐mutant CRC and up‐regulated in pancreatic cancer cell lines resistant towards selumetinib." (PMID 29101300, 2017).
peritonitis (3 papers, 2015 to 2023). Inflammation of the peritoneum (tissue that lines the abdominal wall and covers most of the organs in the abdomen). "Efferocytosis and SPM production is impaired under conditions where MerTK is cleaved and introduction of a cleavage-resistant MerTK in mice improves inflammation resolution during both peritonitis and myocardial reperfusion." (PMID 29163503, 2017). "To confirm MerTK induction in iMΦs and its functional significance, we switched to the LPS-induced peritonitis model, in which peritoneal macrophages could be extracted without collagenase digestion (which may affect cell surface MerTK expression)." (PMID 36422999, 2023).
sarcoma (3 papers, 2017 to 2025). A usually aggressive malignant neoplasm of the soft tissue or bone. "In other cancer types, p-MerTK was found in 18.7% biliary tract cancer (3/16), 27.6% (8/29) of sarcoma, 4.3% (2/46) of genitourinary cancer." (PMID 29285287, 2017). "Besides playing roles in the regulation of immunity, AXL and MERTK provide growth and survival signals to the tumor cells directly.Sarcomas are a mesenchymal tumor type where elevated AXL and MERTK expression has been observed." (PMID 33425754, 2020). "Based on this, we evaluated INCB081776 for antitumor activity in sarcoma PDX models that expressed AXL and/or MERTK." (PMID 33425754, 2020).
schizophrenia (3 papers, 2021 to 2024). A major psychotic disorder characterized by abnormalities in the perception or expression of reality. "MEGF10 and MERTK, which both have been linked to schizophrenia in association studies, encode phagocytic receptors trigger phagocytosis of target debris upon phosphatidylserine recognition." (PMID 33670154, 2021).
type 1 diabetes (3 papers, 2023 to 2025). "On the other hand, a study focusing on the type 1 diabetes NOD mouse model, and assessing granzyme B and IFN-γ production as markers of CD8+ and CD4+ T-cell activation following MERTK inhibition with UNC2025 challenge, found incomplete penetrance." (PMID 37958886, 2023).
acute kidney injury (2 papers, 2013 to 2025). Sudden and sustained deterioration of the kidney function characterized by decreased glomerular filtration rate, increased serum creatinine or oliguria. "KTRMs exhibit up-regulated expression of MerTK, FcγRI, FcγRI/II, and FcγRIV under pathological conditions, such as acute kidney injury (AKI)." (PMID 40230850, 2025). "Patients with renal failure (n = 5) presented higher values of GAS6 (42.5 ± 4.0 ng/mL vs 31.2 ± 1.5 ng/mL; P = 0.023); MerTK (31.4 ± 7.3 ng/mL vs 20.1 ± 1.4 ng/mL; P = 0.024); and Tyro3 (4.6 ± 0.4 ng/mL vs 3.5 ± 0.2 ng/mL; P = 0.031)." (PMID 23497733, 2013).
asthma (2 papers, 2024). "Finally, we found that MerTk-/- AMs had significantly higher Axl expression than WT AMs, suggesting that the Axl receptor is both essential for clearing apoptotic cells and controlling inflammation during silicosis, in agreement with what was found in asthma and influenza virus infection." (PMID 38774866, 2024).
autosomal recessive retinitis pigmentosa (2 papers, 2014 to 2017). Autosomal recessive retinitis pigmentosa (RP) is an autosomally recessive inherited retinal dystrophy leading to progressive loss of the photoreceptors and retinal pigment epithelium and resulting in blindness usually after several decades. "Positional cloning has identified mutation of c-mer proto-oncogene tyrosine kinase (MERTK) in RCS rat and mutations in the human MERTK gene are responsible for some cases of autosomal recessive retinitis pigmentosa." (PMID 25119659, 2014).
brain glioma (2 papers, 2021 to 2024). A malignant glioma that involves the brain. "Similar to the cardiovascular system, our big data analytics show that MerTK expression is significantly lower in several common brain disorders including brain glioma, neuroblastoma, and schizoaffective disorder." (PMID 38341954, 2024).
cervical cancer (2 papers, 2020). A primary or metastatic malignant neoplasm involving the cervix. "Furthermore, we observed MerTK expression in situ in multiple solid tumor immune infiltrates such as in breast, ovary, uterus, and cervix cancer, as well as in prostate, skin, head, and neck cancer." (PMID 33101282, 2020).
coronary artery disease (2 papers, 2021 to 2024). "However, whether the macrophage differential polarization and MerTK expression vary in coronary artery disease (CAD) patients remain unknown." (PMID 33761885, 2021).
demyelinating disease (2 papers, 2016 to 2020). A broad group of disorders that affect the myelin sheaths that cover the neurons. "MERTK has been established as an MS susceptibility gene and is part of a family of receptor tyrosine kinases known to be involved in the pathogenesis of demyelinating disease." (PMID 26990204, 2016). "Taken together, our study showed that the important regulators of myelin clearance, MerTK and Axl, are significantly upregulated after electroacupuncture treatment, and it could be an underlying mechanism for the effect of electroacupuncture in combating demyelinating diseases." (PMID 32714402, 2020).
Ewing sarcoma (2 papers, 2024). A small round cell tumor that lacks morphologic, immunohistochemical, and electron microscopic evidence of neuroectodermal differentiation. "We show that MERTK is present on Ewing sarcoma cells and that MRX-2843 has therapeutic activity against these cells." (PMID 39199601, 2024). "Here, using phospho-profiling, we find Ewing sarcoma cells treated with chemotherapeutic agents activate TAM (TYRO3, AXL, MERTK) kinases to augment Akt and ERK signaling facilitating chemoresistance." (PMID 38906855, 2024).
kidney failure (2 papers, 2013 to 2024). An acute or chronic condition that is characterized by the inability of the kidneys to adequately filter the blood. "We report broad abnormalities of MerTK expression in an array of human diseases including inflammation, cancer, diabetes, kidney failure, hepatitis, and diseases of the brain, cardiovascular system and thyroid in addition to aging." (PMID 38341954, 2024).
neuroblastoma (2 papers, 2021 to 2024). Neuroblastoma (NB) is the most common solid, extracranial childhood tumor. "MerTK expression in the peripheral nervous system is significantly increased in diabetic nephropathy, glaucoma, and ocular hypertension, whereas expression is 6.8 % lower (p = 0.0071) than control in neuroblastoma." (PMID 38341954, 2024).
Obesity (2 papers, 2024 to 2025). Accumulation of substantial excess body fat. "A clinical study on centripetal obesity further confirmed that obesity, particularly when fat is predominantly deposited around the abdominal area, is associated with the cleavage of MERTK by ADAM17 to produce soluble MERTK." (PMID 40458640, 2025). "MerTK expression in muscle only is altered in certain diseases including cerebral palsy, inclusion body myositis, insulin resistance, musculoskeletal disease, overlap myositis, and obesity." (PMID 38341954, 2024).
osteoporosis (2 papers, 2022 to 2023). A condition of reduced bone mass, with decreased cortical thickness and a decrease in the number and size of the trabeculae of cancellous bone (but normal chemical composition), resulting in increased fracture incidence. "As MERTK-RHOA-ROCK signaling interferes with WNT signaling downstream of Sclerostin, activation of MERTK could represent a potential resistance mechanism for Sclerostin-directed therapy in osteoporosis and other bone diseases." (PMID 38203403, 2023). "Further work is warranted to dissect the regulation of the MERTK vs. TYRO3 pathway in osteoblasts in health and disease conditions, including osteoporosis." (PMID 36509738, 2022).
pneumonia (2 papers, 2019 to 2020). An acute, acute and chronic, or chronic inflammation focally or diffusely affecting the lung parenchyma, caused by an infection in one or both of the lungs (by bacteria, viruses, fungi, or mycoplasma.). "Specifically, we examined MERTK function in normal and inflammatory conditions using an in vitro model of cultured human endothelial cells and an in vivo mouse model of acute pneumonia." (PMID 31805065, 2019).
renal cell carcinoma (2 papers, 2019 to 2024). "For example, MerTK is more highly expressed in chronic allograft nephropathy, focal segmental glomerulosclerosis, and renal cell carcinoma, while expressed less in benign familial hematuria, chronic kidney failure, and renal Wilms' tumor." (PMID 38341954, 2024). "Thus, our results suggest that both SAV1 and MERTK contribute to Akt activity regulations, and SAV1 is a critical component for MERTK inhibitor-mediated suppression of Akt activation in renal cell carcinoma." (PMID 30944303, 2019).
thyroid cancer (2 papers, 2025 to 2026). "MR analysis confirmed MERTK and MSR1 as genetic risk factors for thyroid cancer progression, whereas TNFSF12 exhibited protective effects." (PMID 41930700, 2026). "PROS1 from CAFs and tumor cells facilitated the migration and invasion of thyroid cancer cells expressing MERTK, emphasizing the significance of the PROS1/MERTK signaling pathway in PTC progression both in vitro and in vivo." (PMID 40433916, 2025).
acute leukemia (1 paper, 2024). A clonal (malignant) hematopoietic disorder with an acute onset, affecting the bone marrow and the peripheral blood. "In acute leukemia models, however, Mertk-/- or pharmacologic MERTK inhibition had similar effects, providing strong evidence that MERTK inhibition is sufficient to elicit anti-tumor immunity." (PMID 39062902, 2024).
alcohol abuse (1 paper, 2016). The use of alcoholic beverages to excess, either on individual occasions ("binge drinking") or as a regular practice. "When adjusting for age, tumor stage, HPV, alcohol abuse and smoking the Cox regression model showed no significantly increased hazard ratio for patients with medium/high MERTK expression (p = 0.327, Hazard ratio = 1.215)." (PMID 27081701, 2016).
ascending aortic aneurysms (1 paper, 2025). "Here, we mainly focused on ascending aortic aneurysms and dissections (AAAD) and investigated the role of endothelial MerTK in AAAD progression." (PMID 39744231, 2025).
autism (1 paper, 2017). Persistent deficits in social interaction and communication and interaction as well as a markedly restricted repertoire of activity and interest as well as repetitive patterns of behavior. "Developmentally, astrocytes contribute to synaptic pruning by actively removing synapses via MEFG10 and MERTK pathways, or by tagging synapses for elimination by microglia via upregulation of C1q protein, loss of this function could lead to over- or under-pruning of synapses as observed in autism." (PMID 29234492, 2017).
autosomal dominant polycystic kidney (1 paper, 2024). "On the contrary, MerTK expression is significantly higher in skin of humans with autosomal dominant polycystic kidney, Down syndrome, frontotemporal lobar degeneration, type 1⁄2 diabetes mellitus, and urticaria." (PMID 38341954, 2024).
B-cell lymphoma (1 paper, 2020). "We show that MERTK expression is largely restricted to the macrophages of human BL and of murine models of SS B-cell lymphoma and that it is upregulated in SS-TAMs as compared to the germinal center or paracortical macrophages of normal lymph nodes." (PMID 32973744, 2020).
bladder tumours (1 paper, 2019). "Consistent with our results for human bladder tumours, TYRO3 was the TAM receptor most frequently expressed in UBC cell lines (in 21 out of 25 cell lines), followed by AXL (13/25) and MERTK (7/25)." (PMID 30765874, 2019). "Consistent with this general higher level of expression of TYRO3 in bladder tumours compared to normal samples, TYRO3 expression was detected in most of the UBC cell lines, whereas AXL and MERTK had more heterogeneous expression patterns in UBC cell lines." (PMID 30765874, 2019).
brain injury (1 paper, 2025). Acute and chronic (see also brain INJURIES, CHRONIC) injuries to the brain, including the cerebral hemispheres, CEREBELLUM, and brain STEM. "This insight suggests that targeting MerTK-mediated phagocytosis may represent a potential therapeutic approach in neonatal hypoxia-ischemic brain injury." (PMID 41369351, 2025).
cervix squamous cell carcinoma (1 paper, 2020). "MerTK expression was also observed in immune infiltrate in other tumor types such as in pancreas duct adenocarcinoma, in head and neck, skin and cervix squamous cell carcinoma, in ovary, uterus, and prostate adenocarcinoma as well as in kidney clear cell and granular cell tumors." (PMID 33101282, 2020).
chronic kidney failure (1 paper, 2024). "In gland diseases, we found that, compared with normal control, MerTK expression is 37.4 % higher (p < 0.0001) in aldosterone producing adenoma and 25.4 % higher (p < 0.0001) chronic kidney failure, while is 10.1 % lower (p = 0.0049) in hidradenitis suppurativa." (PMID 38341954, 2024).
cognitive decline (1 paper, 2022). "When using change in cognition as an outcome, we found that MERTK and CST7 predicted less pronounced cognitive decline over time in A+T+ individuals after FDR corrections." (PMID 37118533, 2022). "Similarly, higher levels of AXL, MERTK, GAS6, LPL, CST7 and CSF1 predicted slower tau accumulation and/or cognitive decline in the A+T+ group." (PMID 37118533, 2022).
dissection (1 paper, 2024). The separation and isolation of tissues for surgical purposes, or for the analysis or study of their structures. "An obvious formation of aortic dissection was also found in MerTK-/- mice." (PMID 38646649, 2024).
early-onset retinal dystrophy (1 paper, 2025). "Most MerTk mutations in patients are associated with early-onset retinal dystrophy, so the observation that TUDCA increases MerTk activity can have implications for RPE health and survival." (PMID 40699623, 2025).
epilepsy (1 paper, 2021). A brain disorder characterized by episodes of abnormally increased neuronal discharge resulting in transient episodes of sensory or motor neurological dysfunction, or psychic dysfunction. "Furthermore, in patients with epilepsy, the expression levels of TREM2 and PROS1 (a protein that bridges MerTK and PS and is involved in phagocytosis) were decreased, while the expression of MerTK was increased." (PMID 33583110, 2021).
experimental autoimmune encephalomyelitis (1 paper, 2020). An autoimmune demyelinating disease of the central nervous system that is produced experimentally in animals by the injection of homogenized brain or spinal cord in Freund's adjuvant. "During experimental autoimmune encephalomyelitis (EAE), the mRNA expression of MerTK, Gas6, and Axl significantly increase, whereas Tyro3 and ProS1 remain unchanged." (PMID 33121494, 2020).